CYP19A1 (cytochrome P450 family 19 subfamily A member 1)
Diseases named in the same sentence as CYP19A1 in open-access papers (continued):
Sharing a sentence is not in itself a finding about the gene and the disease.
breast cancer (continued). "Aromatase (CYP19A1) inhibitors are the mainstay therapeutics for the treatment of hormone dependant breast cancer, which accounts for approximately 70% of all breast cancer cases." (PMID 36846364, 2023). "The plasma level of CYP19A1 in patients with breast cancer resistance was lower than that in drug sensitive patients." (PMID 35657638, 2022). "A recent study has shown that miR-19a-3p, which decreases CYP19A1 expression, was overexpressed in breast cancer plasma patients and reduced the sensitivity of ER+ breast cancer cells to one of the AIs, letrozole." (PMID 36555323, 2022). "In breast cancer-associated fibroblasts, the GPER agonist G1 induced CYP19A1 gene expression and increased E2 production via the GPER/EGFR/ERK pathway which in turn promoted proliferation and cell-cycle progression." (PMID 36558071, 2022). "The drug-resistant breast cancer patients CYP19A1 mRNA expression level was significantly downregulated (**P<0.01)." (PMID 35657638, 2022). "On the other hand, authors from Iran found the association between CYP19A1 (rs749292) (also for CYP2C8 (rs1058930), CYP1B1 (rs1056836)) genes’ polymorphisms and increased risk of breast cancer in women in Mazandaran province." (PMID 35160095, 2022). "RNA-seq of 98 breast cancer patients showed that the high expression of CYP19A1 was correlated with the low expression of miR-19a-3p." (PMID 35657638, 2022). "E1 concentrations of AT of premenopausal women with breast cancer correlated positively with CYP19A1 mRNA expressions, supporting that active local synthesis of E1 is an important precursor to estradiol in AT in premenopausal women." (PMID 34133482, 2021). "The high expression of the CYP19A1 gene was related to the increase in WATi and some markers of metabolic function in patients with postmenopausal breast cancer." (PMID 34133482, 2021). "Serum follicle stimulating hormone (FSH) and follicular phase correlated negatively with CYP19A1 mRNA expression in women with breast cancer compared to controls." (PMID 34133482, 2021). "We previously reported that DVL proteins not only localize to the nucleus of breast cancer cells, but it also binds to CYP19A1 promoters and regulates its transcription." (PMID 34659647, 2021). "This systematic review was conducted with the prospect of investigating the potential influence of CYP19A1 gene expression levels in women with breast cancer." (PMID 34133482, 2021). "Epidemiological and experimental evidence indicates that women with malignant tumors of the breast, endometrium, and ovary express high levels of mRNA of CYP19A1 and estrogen receptor (ER) alpha as well as elevated levels of estrogens." (PMID 34133482, 2021). "This systematic review aimed to investigate the influence of CYP19A1 gene expression levels in women with breast cancer." (PMID 34133482, 2021). "Therefore, the elucidation of the CYP19A1 gene expression patterns may enable the characterization of women at high risk for breast cancer, as well as the development of strategies for prognosis and effective treatment, allowing better survival and reduction of disease progression." (PMID 34133482, 2021). "This motivated us to detail, in a systematic review, the studies available in several major databases that investigates the influence of levels of CYP19A1 gene expression in women with breast cancer." (PMID 34133482, 2021). "Numerous studies have examined the expression of several CYP isoforms in breast cancer, including aromatase/CYP19A1, CYP1A1, CYP1B1, CYP2J2, CYP2C, CYP3A, and the CYP4 family." (PMID 32581794, 2020). "Human cytochrome P450 aromatase (AROM, CYP19A1) use androgens as substrates with high specificity and catalyze them to estrogens, and its inhibitors, such as exemestane, were used to treat breast cancer for many years." (PMID 33246450, 2020). "Vinorelbine increased also Cyp19A1 p I.7 expression, the main promoter driving aromatase transcription in endothelial cells in mammary tumors." (PMID 32179814, 2020).
breast cancer (continued). "Regarding tumor characteristics, the group of women with breast cancer recurrence showed a significant reduction in CYP19A1 mRNA in women with HER2-negative tumors compared to those with HER2-positive tumors." (PMID 32460723, 2020). "In women with breast cancer, abundance of CYP19A1 transcript was positively correlated with HSD11B1 mRNA expression (r = 0.54; P = .0326)." (PMID 31853538, 2020). "Overexpression of CSMD1 increased CYP19A1 expression levels in breast cancer cells and human adipocytes." (PMID 32701512, 2020). "The CYP19A1 gene has been studied as a prognostic marker of breast cancer due to its genetic control in estrogen biosynthesis." (PMID 32460723, 2020). "Variants in patients with breast cancer have also been correlated with body mass index, waist to hip ratio, and expression of COX-2, IL-6, and Cyp19A1 in breast adipose tissue." (PMID 32708725, 2020). "This indicated CYP19A1 as a potential indicator for the tumor-promoting role of TOX3 in breast cancer." (PMID 33716953, 2020). "In this cross-sectional study, CYP19A1 gene expression was quantified by RT-PCR in the peripheral blood of 146 women with breast cancer who were first divided into two groups according to the expression of CYP19A1 (low and high); each group had 73 patients." (PMID 32460723, 2020). "We previously demonstrated that DVL proteins bind multiple CYP19A1 tissue-specific promoters in multiple breast cancer cells including MDA-MB-231 and MDA-MB-468 cells." (PMID 31700102, 2019). "Aromatase (CYP19A1) converts androstenedione and testosterone into estrogens and is a target for the treatment of breast cancer." (PMID 31533365, 2019). "The inhibition of CYP17A1 and CYP19A1 by curcuminoids provides a template for structure modification to produce effective and safe compounds that can target prostate cancer as well as breast cancer." (PMID 31533365, 2019). "Relative CYP19A1 mRNA expression levels were quantified in primary tumor tissue samples of 100 breast cancer patients." (PMID 29363090, 2018). "We quantified CYP19A1 mRNA expression levels in 15 human breast cancer cell lines and in four untransformed breast epithelial cell lines." (PMID 29363090, 2018). "Mean CYP19A1 expression levels were found to be significantly elevated in breast tumor tissue samples of patients with an age at breast cancer onset ≥ 50 years (1.9-fold; P = 0.007) and in postmenopausal patients (1.7-fold; P = 0.047)." (PMID 29363090, 2018). "Breast cancer cell lines tended to have 4.5-fold lower mean CYP19A1 expression levels compared to normal, untransformed breast epithelial cell lines (P = 0.06, t test)." (PMID 29363090, 2018). "Accordingly, fibroblastoid breast cancer cell lines exhibited a 5.9-fold higher mean CYP19A1 expression compared to cell lines with an epithelial phenotype (P = 0.006)." (PMID 29363090, 2018). "Liu and colleagues showed that Norendox inhibited CYP2C19 and aromatase (CYP19A1) activity, while CYP19A1 activity was also inhibited by Endox pointing to a dualistic inhibitory effect of Endox on estrogen-driven breast cancer cells." (PMID 29285606, 2018). "The report, herein, uncovers a new regulator of CYP19A1 transcription and for the first time demonstrates that DVL, a critical mediator of WNT signaling, contributes to aberrant breast cancer-associated estrogen production." (PMID 30479694, 2018). "Specific roles for CYP3A4 and CYP19A1 in breast cancer therapy response have been reviewed, but only preliminary considerations have been made for modeling the concurrent and opposing activities of these enzymes on therapies within the same treatment regimen." (PMID 29783934, 2018). "A shortened disease-free survival of unselected breast cancer patients with a high CYP19A1 mRNA expression has been reported previously." (PMID 29363090, 2018).
breast cancer (continued). "Exemestane (EXE) treats estrogen receptor positive (ER+) breast cancer in postmenopausal women by inhibiting the estrogen‐synthesizing cytochrome P450 CYP19A1." (PMID 28603632, 2017). "Another SNP, rs12592697, in the intronic region of CYP19A1 was associated with differences in allele frequency between NHW and Hispanic women with breast cancer." (PMID 27994616, 2016). "For example, in breast cancer cell lines, SIRT1 has been shown to positively regulate the CYP19A1 gene, which encodes the aromatase protein." (PMID 25569080, 2015). "Increased CYP19A1 expression has been correlated with poor prognosis in breast cancer, and the decreased expression observed in the current study further supports that MCF-7 cells are becoming more differentiated when cultured in scaffold-free conditions." (PMID 26267486, 2015). "In our study we found that five common estrogen responsive genes, including CYP19A1 and ESR2 that were associated with all three EDCs-PCBs, phthalates and BPA, breast cancer, and endometriosis." (PMID 26512648, 2015). "Case-control studies of breast cancer risk related to ESR1 rs2234693 and in relation to CYP19A1 rs936306 are conflicting." (PMID 19630952, 2009). "Likewise, CYP19A1 rs936306 may be associated with breast cancer disease-free survival." (PMID 19630952, 2009). "Furthermore, Exemestane, letrozole, and anastrozole, as typical third-generation CYP19A1 inhibitors, have been investigated in breast cancer treatment by targeting CYP19A1." (PMID 41050076, 2025). "Many factors in adipose tissue, including inflammatory mediators, adipokines, and cytokines, increase the expression of aromatase (CYP19A1), key enzymes for estrogen synthesis, and local production of estrogen, which contributes to breast cancer development and progression." (PMID 37047797, 2023). "According to the previous studies, CSMD1 and CYP19A1 SNPs could, in fact, be used as predictive markers of anastrozole response in breast cancer." (PMID 35457144, 2022). "In our study, we first determined that the expression of CYP19A1 in the plasma of drug-resistant breast cancer patients was significantly upregulated, indicated that the effect of CYP19A1 on drug sensitivity in breast cancer may be bidirectional." (PMID 35657638, 2022). "CCK-8 cell activity test showed that different level of CYP19A1 in BT-474 cells could significantly affect the activity of breast cancer cells." (PMID 35657638, 2022). "Altered levels of CYP19A1 gene expression may be related to unfavorable outcomes and increased aggressiveness in breast cancer." (PMID 34133482, 2021). "In breast cancer patients treated with aromatase inhibitors, the screening of CYP19A1, CYP17A1, CYP27B1, TCLA1, RANK/RANKL/OPG, and ESR1/ESR2 variants may be of some utility to optimize positive effects and reduce ADRs." (PMID 34948113, 2021). "Treatment with the vitamin D analog EB1089 effectively inhibits aromatase-dependent growth of breast cancer cells by dissociating BAZ1B from the CYP19A1 promoter in a vitamin D receptor (VDR)-dependent manner, suggesting that BAZ1B is a potential drug target in breast cancer." (PMID 34736517, 2021). "High CYP19A1 expression is critical for the development of breast cancer." (PMID 33836687, 2021). "The purpose of this study was to elucidate the interplay between intratumoral levels of AhR and aromatase, patient characteristics (including AhR and CYP19A1 genotypes), clinicopathological features, and prognosis in breast cancer patients receiving adjuvant treatments." (PMID 34094928, 2021). "Some authors have not shown an association between CYP19A1 gene expression in women with breast cancer and HER2 receptor status." (PMID 32460723, 2020). "It has been described that docetaxel decreases Cyp19A1 mRNA levels in mammary tumors, thus indicating that the anticancer actions of chemotherapy might account, at least partially, on its ability to suppress estrogens synthesis." (PMID 32179814, 2020).
breast cancer (continued). "Thus, the controversies surrounding the gene expression of CYP19A1 in breast tumor studies and, to the best of our knowledge, the absence of studies analyzing the peripheral blood of women with recurrent breast cancer led to the design of this study." (PMID 32460723, 2020). "The molecular structure of curcuminoids could be modified to generate better lead compounds with inhibitory effects on CYP17A1 and CYP19A1 for potential drugs against prostate cancer and breast cancer." (PMID 31533365, 2019). "The CC genotype of rs10046, one of the most extensively studied CYP19A1 candidate SNPs, was found associated with a longer disease-free survival of premenopausal, but not postmenopausal breast cancer patients." (PMID 29363090, 2018). "Single nucleotide polymorphisms (SNPs) in the estrogen receptor 1 (ESR1) and cytochrome P450 19A1 (CYP19A1) genes have been associated with breast cancer risk, endocrine therapy response and side effects, mainly in postmenopausal women with early breast cancer." (PMID 27825388, 2016). "Based on the 45 290 European-ancestry breast cancer cases and 41 880 controls from the BCAC iCOGS study, none of the 171 CYP19A1 locus SNPs with P<10−4 for endometrial cancer were associated with breast cancer (minimum P=0.0033, data not shown)." (PMID 26574572, 2016). "Despite higher endogenous E2 concentration also being a known risk factor for breast cancer, candidate SNP studies of CYP19A1 have not reported an association with breast cancer." (PMID 26574572, 2016). "We hypothesized that SNPs in the aromatase gene CYP19A1 and SNPs in other genes for drug and estrogen metabolism may be used as treatment predictive markers for adjuvant treatment with AI in primary breast cancer patients." (PMID 27029552, 2016). "The up-regulation of CYP19A1 expression has been observed to contribute to breast cancer." (PMID 25689428, 2015). "The importance of the aromatase enzyme (CYP19A1 gene) to catalyze the conversion of androgens to estrogens in many human tissue sites that are known to stimulate cellular proliferation in breast cancer represents one of the most crucial health issues of our time." (PMID 26798508, 2015). "Total PCBs associated with AREG, CYP19A1, ESR2, FOS, KRAS and STC2 genes; PCB 126 associated with AREG, CYP19A1, and STC2 genes and PCB 15 associated with CYP19A1, EGFR, ESR2, FOS, and IGF1 genes overlapped with 17β-estradiol, breast cancer, and endometriosis." (PMID 26512648, 2015). "The protective role of rs17601876 in the CYP19A1 gene underscores the critical role of aromatase in modulating the estrogen level, which is a key driver in the development and progression of hormone-dependent cancers such as endometrial cancer and breast cancer." (PMID 40141105, 2025). "Our results describing the inhibitory effect of curcuminoids on CYP17A1 as well as CYP19A1 indicate that some of the effects of curcuminoids seen in studies on prostate cancer and breast cancer cell lines, may be due to inhibition of steroidogenic cytochrome P450 enzymes." (PMID 31533365, 2019). "Moreover, immunological investigation further revealed that targeting the whole CYP19A1-ESR axis might cause the inactivation of anti-tumor immune response, which largely attenuated its application prospects in breast cancer." (PMID 31741086, 2019). "Inhibition of CYP17A1 and CYP19A1 activities by curcuminoids indicate similar molecular entities or modified compounds based on core structures of curcuminoids could be explored as potential treatments for prostate cancer by targeting CYP17A1 and for breast cancer by targeting CYP19A1." (PMID 31533365, 2019). "In contrast, high CYP19A1 expression was highly significantly associated with a poor overall, disease-free, and metastasis-free survival in estrogen receptor-positive but not negative breast cancer patients." (PMID 29363090, 2018).
breast cancer (continued). "We identified 10 association studies between CYP19A1 variants and breast cancer patient outcomes after AI therapy, but we could find no such pharmacogenetic reports in endometrial cancer." (PMID 28487654, 2017). "In light of the aggregate of findings regarding CYP19A1 misexpression from gonadal promoters in breast cancer cases, Demura and Bulun postulated CYP19A1 pII/I.3 hypomethyaltion may contribute to the phenomenon of ‘promoter switching’ and inter-individual variability in lifetime estrogen exposure." (PMID 24649863, 2014). "Since polymorphisms in CYP19A1 impact estrogen levels, we hypothesized that the presence of functional polymorphisms in this gene would be associated with AIAA among postmenopausal breast cancer survivors on AI therapy." (PMID 21251330, 2011). "Breast cancer can be prevented by eating foods that change the activity of certain cytochrome P450 enzymes, including CYP1A1, CYP1A2, CYP1B1, CYP2B6, CYP3A4, CYP19A1, and CYP24A1." (PMID 36571647, 2022). "Its expression was closely related to Letrozole resistance in breast cancer therapy Through analysis of 4 databases, 7 miRNAs that can target ESR1 were screened out, and 4 miRNAs that can target CYP19A1 were screened out through bioinformatics analysis." (PMID 35657638, 2022). "LINC00094 promotes the expression of CYP19A1, the target gene of miR-19a-3p, and inhibits the EMT process of breast cancer, ultimately promoting the sensitivity of ER-positive breast cancer cells to Letrozole." (PMID 35657638, 2022). "In our work, TOX3 promoted estrogen biosynthesis by upregulating genes related to the development of breast cancer, including FSHR, CYP19A1, and BMP6." (PMID 33716953, 2020). "To assess the role of CSMD1 in AI response in breast cancer cells, we used the MCF7/AC1 cell line because of its high expression of the AI target CYP19A1." (PMID 32701512, 2020). "Considered the pathophysiologic functions of CYP19A1 and ESR1/ESR2-mediated signaling pathway in breast cancer seem as more complicated than what we have already known, more precise evaluation will be needed in urgent." (PMID 31741086, 2019). "Five genes—CYP19A1, EGFR, ESR2, FOS, and IGF1—were common among all three EDCs–PCB 153, phthalates and BPA, breast cancer, and endometriosis." (PMID 26512648, 2015). "All three EDCs–PCB 153, phthalates, and BPA influenced five common genes—CYP19A1, EGFR, ESR2, FOS, and IGF1—in breast cancer as well as in endometriosis." (PMID 26512648, 2015). "Five genes—CYP19A1, EGFR, ESR2, FOS, and IGF1—were common among all three EDCs–PCBs, phthalates and BPA, 17β-estradiol, breast cancer, and endometriosis." (PMID 26512648, 2015). "In this way, CYP19A1 is located in the 21.2 region of the long arm of chromosome 15 (15q21.2), and this region has been reported to be a frequent target of allelic imbalance in advanced breast carcinomas, and which could affect the frequency distribution of the allelic variants." (PMID 20144226, 2010). "The discovery of the off-target CYP11B2 inhibition effect of fadrozole, an approved non-steroidal cytochrome P450 19A1 (CYP19A1) inhibitor for breast cancer management, led to the development of its derivative, 5R-fadrozole." (PMID 39170743, 2024). "We first detected the CYP19A1 expression from 26 patients plasma with drug-resistant breast cancer, comparing with 72 patients with non-drug-resistant patients." (PMID 35657638, 2022). "Barh demonstrated that in silico analysis, apart from repressing HMGA2, RAS, and MYC, let-7 may also target CYP19A1, ESR1, and ESR2, thereby potentially blocking estrogen signaling in ER-positive breast cancers." (PMID 34442460, 2021). "Regarding the negative expression of the CYP19A1 gene in the follicular phase of women with breast cancer, the authors suggested the existence of a deregulation of the estrogen synthesis in the TA of the breast with tumor." (PMID 34133482, 2021).